GATA2 (GATA binding protein 2)
Diseases named in the same sentence as GATA2 in open-access papers (continued):
Sharing a sentence is not in itself a finding about the gene and the disease.
lymphedema (41 papers, 2014 to 2025). Excess fluid collection in tissues, causing swelling. "Accompanying constitutional features, such as lymphedema, hydrocele and sensorineural deafness, serve as frequent telltale signs of underlying germline GATA2 variants." (PMID 40664679, 2025). "Monosomy 7 was identified in one of our patients who exhibited features of MDS and lymphedema, with a confirmed GATA2 mutation." (PMID 40358701, 2025). "In other diseases, ERG-dependent transcription has been shown to modulate cardiovascular disease, and germline LOF ERG variants have been reported to lead to lymphedema, see also in ~10-15% of germline GATA2 cases." (PMID 37377909, 2023). "GATA2 deficiency is a disease with a broad spectrum of clinical presentation, ranging from lymphedema, deafness, pulmonary dysfunction to miscarriage and urogenital anomalies, but it is mainly recognized as an immune system and bone marrow disorder." (PMID 35769478, 2022). "The reason that haploinsufficient GATA2 mutations cause lymphedema is due to a crucial role for GATA2 in the development and maintenance of lymphatic vessel valves." (PMID 34387894, 2021). "Lymphedema, particularly in an adolescent or young adult with cytopenia, is highly suggestive of GATA2 deficiency." (PMID 33066218, 2020). "We need better insight into the molecular mechanisms of GATA2 activity to understand the causes of lymphedema in Emberger syndrome patients." (PMID 31582413, 2019). "Heterozygous mutations in the zinc-finger transcription factor GATA2 are associated with an array of hematopoietic disorders and lymphedema." (PMID 31582413, 2019). "In summary, early-onset lymphedema with incomplete penetrance is associated with GATA2-heterozygous mutations." (PMID 31582413, 2019). "Previous work identified inactivating mutations in the GATA2 gene as causative of Emberger syndrome, which is an autosomal dominant condition with lymphedema in lower limbs and genitalia." (PMID 29666442, 2018). "Approximately 30% of patients carrying mutations in GATA2 develop lymphedema (n=14 from 8 families)." (PMID 29125824, 2017). "Another study reported lymphedema with incomplete penetrance in 3 out of 10 patients with GATA2 mutations." (PMID 29125824, 2017). "Heterozygous familial or sporadic GATA2 mutations cause a multifaceted disorder, encompassing susceptibility to infection, pulmonary dysfunction, autoimmunity, lymphoedema and malignancy." (PMID 25707267, 2015). "Although not genetically tested, the family history of the patient ́s mother was also suggestive of GATA2 deficiency: she had a long history of lymphedema of both legs following gynecological surgery, had recurrent mycobacterial infections and died at the age of 58 because of a bacterial pneumonia." (PMID 38993648, 2024). "In this case, GATA2 deficiency was suspected 7 years after the initial presentation with pancytopenia based on the typical extra-hematological manifestations with primary lymphedema of the genitals as well as palmar and plantar warts." (PMID 38993648, 2024). "Other clinical features characteristic of GATA2 deficiency are lymphedema and sensorineural deafness, showing the crucial role of GATA2 in the development of both lymphatic vessels and lymphatic valves, as well as of semicircular canals and perilymphatic spaces." (PMID 35769478, 2022). "Clinical features of GATA2 deficiency may include recurrent infections, atypical mycobacterial infections, warts, pulmonary alveolar proteinosis, or lymphedema." (PMID 35356204, 2022). "Approximately 11-30% of people with mutated GATA2 develop lymphedema." (PMID 31582413, 2019). "Only some patients with mutations in GATA2 will develop lymphedema." (PMID 31582413, 2019). "Mutations in the transcription factor GATA2 cause lymphedema." (PMID 31582413, 2019).
lymphedema (continued). "In humans, haploinsufficiency of GATA2 caused by heterozygous spontaneous or autosomal dominant mutations causes a wide spectrum of clinical implications ranging from lymphedema, predisposition to mycobacterial, and viral infections to bone marrow failure with MDS/AML." (PMID 28747912, 2017). "In another cohort of 57 patients with GATA2 mutations, 11% developed lymphedema." (PMID 29125824, 2017). "One of the latest nationwide study, an Italian cohort of 30 patients with GATA2 deficiency, revealed new clinical phenotypes—pilonidal cyst/sacrococcygeal fistula, cholangiocarcinoma, and gastric adenocarcinoma—and show that lymphedema may be associated with null/regulatory GATA2 mutation." (PMID 41322420, 2025). "The diagnosis of MDS may be the first presentation of the underlying germline predisposition or may be the hematologic presentation of a syndrome unrecognized with subtle or non-hematologic manifestations, like short-stature in Shwachman–Diamond syndrome (SDS) or lymphedema in GATA2 deficiency." (PMID 35356204, 2022). "Lymphedema, in particular, is notably present in 11–20% in GATA2 patients; it typically affects the lower limbs and frequently involves the genitals in the form of a hydrocele." (PMID 38993648, 2024). "In particular, mutations in SOX18, PROX1, GATA2, and FOXC2 cause various forms of syndromic lymphedema." (PMID 35806420, 2022). "Next, the endothelial transcription factor GATA2 (GATA binding protein 2) can activate the transcription of genes involved in lymphatic vessel valve development, an impairment function correlated with lymphedema." (PMID 34362022, 2021). "Lymphovenous valve insufficiency is a feature of several lymphedema mouse models with disruptions in genes including Prox1, Foxc2, Cx37, Gata2, Pdpn, or Clec2." (PMID 34055805, 2021). "Several manifestations make up the spectrum of GATA2 deficiency (immunodeficiency, MDS, lymphedema, mycobacterial infections)." (PMID 34633564, 2021). "Mutations associated with the VEGF-C/VEGR3 signaling pathway, including changes in FOXC2, as well as key transcription factors involved in LEC specification, such as Sox-18 and GATA2, contribute to the development of primary lymphedema." (PMID 32510325, 2020). "Consistent with this notion, patients with c.1017+512del28 deletion or a c.1017+572C>T point mutation within the evolutionarily conserved GATA2 intragenic enhancer (divergence ~350 million years ago) have lymphedema and significantly reduced GATA2 expression." (PMID 29035278, 2017). "Interestingly, there is not an absolute correlation between genotype and phenotype in GATA2 deficiency, and patients with the same mutations may exhibit different clinical features ranging from isolated neutropenia or lymphedema to MDS, AML, or severe viral infections." (PMID 28747912, 2017). "Regardless of the several types of mutations leading to GATA2 deficiency, there is no clear association between these mutations and clinical phenotypic expression, except for lymphedema that was linked to the nonsense and deletion mutations." (PMID 41438140, 2025). "Among 108 distinct GATA2 variants (67 novel), null mutations conferred a 1.7-fold increased risk for MDS, had earlier MDS onset compared to other variants (12.2 vs. 14.6 years, p = 0.009) and were associated with lymphedema and deafness." (PMID 40664679, 2025). "have recently challenged the previous notion that lymphedema is never observed in patients with missense mutations, which was considered the sole genotype-phenotype correlation observed in GATA2 deficiency." (PMID 38993648, 2024). "In light of their mother’s medical history with lymphedema and ARDS, which could be secondary to complications related GATA2 deficiency, the GATA2 variant is probably maternally inherited." (PMID 34893945, 2022).
lymphedema (continued). "This study concluded that the GATA2 mutations abolishing enhancer-binding resulted in the loss of valves due to reduced expression of PROX1 and FOXC2, and strongly suggests that a loss of valves leads to lymphedema in human patients." (PMID 32824219, 2020). "Suggestions that N-terminal frameshift mutations or larger deletions of GATA2 are more likely to cause lymphoedema and non-haematopoietic defects are supported by the larger cohort studies." (PMID 25707267, 2015). "Unlike most congenital forms of lymphoedema, which occur bilaterally as a child begins to walk, patients with GATA2 mutation often describe a precipitating event occurring later and leading to unilateral limb swelling." (PMID 25707267, 2015). "Unlike patients with WILD syndrome, patients with GATA2 deficiency rarely have lymphoedema affecting the face or upper limbs (the swelling is usually confined to one or both lower limbs and the genital region) and do not present with cutaneous lymphovascular malformations or epidermal naevi." (PMID 34916230, 2023). "GATA2-associated familial AML/MDS is frequently characterized by recurrent or atypical bacterial infections and lymphedema, but despite of the distinctive clinical manifestations, AML/MDS with GATA2 predisposition may go unrecognized due to incomplete penetrance and missing family history." (PMID 34633564, 2021). "Similarly, a ‘second hit’ in the targets of GATA2, such as miR-126, might be required to trigger the onset of lymphedema in human patients." (PMID 31582413, 2019). "Thus, there is strong evidence that reduced GATA2 expression leads to lymphedema." (PMID 29035278, 2017). "Additionally, the mutations in GATA2 that underlie Emberger syndrome produced mutant GATA2 proteins that were unable to bind enhancer elements in both the PROX1 and FOXC2 genes that were active only in the valve cells, and only these mutations were associated with lymphedema in patients." (PMID 32824219, 2020).
myeloid neoplasm (37 papers, 2015 to 2025). Proliferation of myeloid cells originating from a primitive stem cell. "We report two families with novel frameshift variants in GATA2 that were incidentally diagnosed with myeloid neoplasms." (PMID 40821825, 2025). "We feel that inclusion of GATA2 should also be considered as this data is likely underestimating the risk of myeloid malignancy and death in individuals with heterozygous GATA2, given the age bias present." (PMID 39501104, 2025). "In this case, chemoresistance likely arose from the coexistence of the GATA2 deficiency and monosomy 7, both of which are independently associated with a poor treatment response in myeloid malignancies." (PMID 40981111, 2025). "This case broadens the spectrum of solid cancers linked to GATA2‐deficiency, emphasizing the need for considering primary immunodeficiency in young patients with myeloid neoplasms or rare skin cancers, facilitating early detection and treatments." (PMID 39614632, 2024). "Among the thirty-one patients, five (16.1%) had causative germline variants predisposing them to myeloid neoplasms (three with GATA2 variants and one each with PGM3 and ETV variants)." (PMID 38137719, 2023). "In one study that reviewed 18 published series (>350 individuals), the penetrance of myeloid neoplasms was estimated to reach 75% in GATA2-mutated carriers, with an increased risk of developing MDS/AML as they aged." (PMID 36900380, 2023). "In this review, we will examine the structural characteristics of the GATA2 gene, its physiological and pathological functions, how GATA2 genetic mutations contribute to myeloid neoplasms, and other potential clinical manifestations." (PMID 36900380, 2023). "By contrast, deleterious SF3B1, U2AF1, NPM1, and FLT3 changes are infrequent in GATA2-mutated myeloid neoplasms." (PMID 36900380, 2023). "Among the thirty-one patients, five (16.1%) had causative germline variants predisposing them to myeloid neoplasms in the GATA2, PGM3, and ETV6 genes, and all of these identified variants have been previously reported." (PMID 38137719, 2023). "Germline mutations in the DDX41 gene, telomere biology disorders, GATA2, and thrombocytopenia-associated disorders are associated with myeloid malignancies in older adults." (PMID 38137443, 2023). "Among the reported phenotypes associated with germline GATA2 variants, myeloid malignancy is the most common phenotype (74.3%) with a median age of onset of 17 years." (PMID 34387894, 2021). "Mutations in transcription factors such as CEBPA, RUNX1, and GATA2 can be seen in myeloid neoplasms, both de novo or with germline predisposition." (PMID 35054439, 2021). "It was estimated that individuals with germline GATA2 mutations have almost 90% risk of developing clinical symptoms and 50–70% risk of developing myeloid neoplasms." (PMID 35054439, 2021). "At the same time, SF3B1 (Splicing Factor 3b Subunit 1), U2AF1 (U2 Small Nuclear RNA Auxiliary Factor 1), NPM1, and FLT3 are rarely mutated in GATA2-mutated myeloid neoplasms." (PMID 35054439, 2021). "After excluding overt myeloid malignancies, bacterial infections were found to be the most common symptoms of GATA2 deficiency." (PMID 34633564, 2021). "In children with myeloid leukemia the gene most often mutated is Gata binding protein 2 (GATA2) and 80% of patients with GATA2 mutations develop myeloid malignancy before the age of forty." (PMID 34713225, 2020). "Mutations of the GATA binding protein 2 (GATA2) gene in myeloid malignancies usually cluster in the zinc finger 1 (ZF1) and the ZF2 domains." (PMID 30190467, 2018). "In sporadic and familial myeloid malignancies, high GATA2 expression and acquired or inherited mutations of the GATA2 gene have been reported." (PMID 26287967, 2015).
myeloid neoplasm (continued). "The mechanism(s) by which loss-of-function mutations in GATA2 and/or reduced GATA2 levels promote myeloid malignancies remains unclear, but the finding has generated interest in targeting GATA2 for the prognosis or treatment of hematologic disorders." (PMID 39443360, 2024). "In young MCC patients or myeloid neoplasm patients with a history of rare skin cancer, the possibility of primary immunodeficiency must be considered, such as GATA2–deficiency, to allow early detection and the choice of treatment strategies, potentially improving patient outcomes." (PMID 39614632, 2024). "This could be related to the ability of Gata 1 and Gata2 to interact with the myeloid lineage and B-cell regulator PU.1, which, in turn, may underlie the predisposition to myeloid malignancies associated to Gata2 mutation." (PMID 34736527, 2021). "Interestingly, germline deficiencies in GATA2 leads to myeloid malignancies with an immunodeficient phenotype." (PMID 34422660, 2021). "Currently, it remains unclear how germline GATA2 loss-of-function mutations result in myeloid neoplasms." (PMID 29881389, 2018). "Because high levels of GATA2 are linked to poor outcomes in myeloid malignancies and GATA2 was among the genes most differentially regulated by HMGA1, functional studies were performed to determine whether HMGA1 depends upon GATA2 and downstream networks for leukemic transformation in MPN models." (PMID 40076747, 2025). "Identification of GATA2 myeloid neoplasms requires a specific approach for management and therapeutic strategies." (PMID 40299403, 2025). "In conclusion, a germline predisposition to myeloid neoplasms occurred in ~16% of young-onset MDS patients and was largely associated with primary immunodeficiencies, including GATA2 deficiency." (PMID 38137719, 2023). "In the list of germline mutations with predisposition to myeloid neoplasms, many encode known master transcription factors, such as CEBPA, RUNX1, and GATA2." (PMID 35054439, 2021). "Other co-mutations often seen in myeloid neoplasms with germline RUNX1 are in DNMT3A, FLT3, GATA2, PHF6 (PHD finger protein 6), BCOR (BCL6 Corepressor), WT1, and TET2." (PMID 35054439, 2021). "We discuss the structural characteristics of the GATA2 gene and describe how its genetic alterations might contribute to the onset of myeloid neoplasms as a result of aberrant induced hematopoiesis." (PMID 36900380, 2023). "Moreover, GATA2 and MEIS1 knockdown in the leukemic cell lines K562 and Kasumi-1 reduced the frequency of CFU-Cs, verifying that GATA2 and MEIS1 could be potential therapeutic targets for ASXL1 mutation–associated myeloid malignancies." (PMID 37917239, 2024). "The median age of GATA2‐driven myeloid malignancy (GDMM) onset is 17 years, with onset ranging from 0 to 78 years of age, with ~75% of identified GATA2 carriers developing a malignancy." (PMID 34387894, 2021). "The previously reported symptomatic patients with the GATA2 S447R were diagnosed with myeloid neoplasms (MDS, AML) and aplastic anemia, but none presented solid cancers." (PMID 39614632, 2024). "Somatic GATA2 mutations rarely occur in GDMM (i.e., biallelic) unlike for germline RUNX1, CEBPA, and DDX41‐driven myeloid malignancies where biallelic mutations are common." (PMID 34387894, 2021).